RNU7-128P (RNA, U7 small nuclear 128 pseudogene)
Gene: Small nuclear RNA gene on chromosome 3 (48,180,328 to 48,180,389, forward strand). Ensembl gene ENSG00000253056.
Homologues: Orthologues: macaque U7 (97% identical). Paralogues in human: RNU7-14P (89% identical), RNU7-28P (89% identical), RNU7-45P (89% identical), RNU7-7P (89% identical), RNU7-147P (87% identical), RNU7-18P (87% identical), RNU7-23P (87% identical), RNU7-3P (87% identical), RNU7-6P (87% identical), RNU7-11P (85% identical), RNU7-13P (85% identical), RNU7-21P (85% identical), and 142 more.